STAG3L3 (STAG3 cohesin complex component like 3 (pseudogene))
Synonyms: STAG3L3P
Gene: Transcribed unprocessed pseudogene on chromosome 7 (72,998,027 to 73,003,730, reverse strand). Ensembl gene ENSG00000174353.
Subcellular location: Nucleus